CDKN1B (cyclin dependent kinase inhibitor 1B)
Diseases named in the same sentence as CDKN1B in open-access papers (continued):
Sharing a sentence is not in itself a finding about the gene and the disease.
cancer (388 papers, 2002 to 2026). A tumor composed of atypical neoplastic, often pleomorphic cells that invade other tissues. "In excised murine tumors, IHC revealed an increase in dormancy gene CDKN1B-encoded protein p27 and a decrease in proliferation marker Ki67, recapitulating the inverse expression observed in quiescent cancer cells." (PMID 39199676, 2024). "It was also found that miR-222 targets and negatively regulates CDKN1B (encoding p27kip1), a negative regulator of cell cycle progression in PCa and many other cancers." (PMID 37370750, 2023). "As a ubiquitin ligase subunit, SKP2 can target to degrade CDKN1B, promote the transformation of cells from the G1 phase to the S phase, and then cause the growth and proliferation of cancer cells; this is considered the typical function of SKP2." (PMID 37308972, 2023). "Among the CDKN1B mutations found in cancers, many are nonsense or small deletions/insertions causing the synthesis of truncated p27 variants, with deleterious effects on protein levels and functions." (PMID 33316141, 2021). "As a result, somatic mutations in the CDKN1B gene are associated with cancer development, aggressive tumors, and poor prognosis." (PMID 34063545, 2021). "The p27 protein encoded by the CDKN1B gene is a particularly attractive target since it is already known to represent a cancer driver due to its strong involvement in cell cycle arrest." (PMID 33295144, 2021). "In human cancers inactivation of CDKN1B gene, encoding for p27, is rarely due to mutation or deletion." (PMID 34654798, 2021). "Assembling evidences suggested the intimate association between deficiencies of CDKN1B with array of human cancers." (PMID 32549789, 2020). "Both miRNAs are located in a cluster on the X chromosome; their deregulation is a hallmark of several types of cancer, probably because one of their targets is the cell cycle regulatory protein p27Kip1/CDKN1B." (PMID 32356180, 2020). "The p27(Kip1) protein (encoded by CDKN1B), participates in many signal transduction pathways and mediates tumor suppressor or oncogenic roles in cancer." (PMID 30992462, 2019). "Differential regulation of downstream genes in CMTs with the PIK3CA (H1047R) mutation, such as up-regulated PCK2 and down-regulated CDKN1B, allows cancer cells to utilize an alternative catabolic pathway." (PMID 31842489, 2019). "Our review of the literature and available datasets reporting the mutations of CDKN1B gene in human cancers indicates that these events are generally rare in sporadic cancer, with the exception of LBC, PC, and SI-NET." (PMID 30065701, 2018). "The works on SI-NETs give some interesting new insights on the possible role(s) and significance of CDKN1B mutations in human cancer." (PMID 30065701, 2018). "Yet, the advent of massive parallel sequencing has partially subverted this general understanding demonstrating that, at least in some types of cancer, CDKN1B is mutated in a significant percentage of analyzed samples." (PMID 30065701, 2018). "These molecular and preclinical evidences have acquired particular clinical interest in the last few years, when mutations of CDKN1B gene were unexpectedly identified as driver mutations in selected types of human cancers." (PMID 30065701, 2018). "USP5 loss led to significant increase in p21 (CDKN1A) and p27 (CDKN1B) levels with simultaneous decrease in CyclinD1 in the cancer cells." (PMID 29029505, 2017). "Recent whole genome sequencing data suggest that CDKN1B (the gene encoding for p27) is frequently mutated in some types of human cancer, particularly in luminal breast cancer." (PMID 28377607, 2017).
cancer (continued). "This conclusion is further supported by deregulated cell cycle control and cancer incidence in Rb1G/G; Cdkn1b−/− mice, suggesting loss of multiple pRB dependent proliferative control pathways can be dramatically different than loss of a single pathway." (PMID 28293272, 2017). "Our study further defines the complex role played by p27 in the regulation of cytoskeletal dynamics, migration, EMT and invasion and provides another element to explain why the Cdkn1b gene is rarely mutated in cancer." (PMID 28287395, 2017). "Much attention has been directed to the association between cancer risk and rs2066827 polymorphism of the CDKN1B gene." (PMID 26579796, 2015). "In this study, we investigated the possible association of MEN1 malignant tumours with CDKN1B V109G polymorphism." (PMID 25824098, 2015). "Down regulation of cyclin-dependent kinase inhibitor 1B (CDKN1B or also known as p27) is reported in approximately 60% of human cancer and also found to be associated with poor prognosis and resistance to chemotherapeutic drugs." (PMID 24409284, 2014). "Haploinsufficiency of CDKN1B is strongly implicated in numerous cancer types, the vast majority of lymphatic origin." (PMID 25213837, 2014). "Reduced levels of CDKN1B occur in several cancer types and are generally associated with poor prognoses." (PMID 24605326, 2014). "Loss of CDKN1B expression is a risk factor for disease recurrence and the strongest predictor of cancer-specific survival." (PMID 24605326, 2014). "p27KIP1 expression is often reduced in cancer, and germline mutations have been identified in CDKN1B in patients affected with a syndrome (MEN4) characterized by varying combinations of tumors in endocrine glands." (PMID 23555276, 2013). "The Cdkn1b gene is rarely mutated in human cancers but decreased concentrations of p27Kip1 are implicated in human tumorigenesis." (PMID 18941537, 2008). "While CDKN1B mutations are rare, decreased levels of p27, often mediated by aberrant activity of E3 ligases, are likely to contribute to tumorigenesis and poor prognosis in various cancers." (PMID 40002221, 2025). "This phosphorylation at S12 appears to be responsible for the loss of CDKN1B function and may be associated with cancer." (PMID 40806592, 2025). "In addition, MPM_31 displayed an abnormal electrophoretic migration of p27 (two bands), which we found to be associated with a I119T mutation of one CDKN1B allele that was previously reported in other cancers." (PMID 36453028, 2024). "Interestingly, both AKT3 and CDKN1B are linked to clinical head size syndromes and cancer risk and contain, respectively, 3′-UTR variants and an exonic variant that reach genome-wide significance." (PMID 38703765, 2024). "Skp2 was a target for cancer treatment and was implicated in controlling CDKN1B expression." (PMID 37432583, 2023). "In this study, we report a detailed functional characterization of a cancer‐associated CDKN1B missense mutation and evidenced an unexpected and undescribed mechanism by which the genetic change might result in a haploinsufficient phenotype." (PMID 33316141, 2021). "However, due to NGS and genome‐wide association analysis development, CDKN1B has been now found mutated in several cancers." (PMID 33316141, 2021). "Indeed, some human cancers display elevated levels of cytoplasmic CDKN1A or cytoplasmic CDKN1B, which is associated with poor prognosis, and badly response to cisplatin based treatment." (PMID 28231799, 2017). "More importantly 9 new cancer genes were identified; seven of them (ARID1B, CASP8, MAP3K1, MAP3K13, NCOR1, SMARCD1, CDKN1B) carried truncating mutations and were characterized by biallelic inactivation, suggesting that they were potentially recessive cancer susceptibility genes." (PMID 26561834, 2015).
cancer (continued). "miR-222, which had increased expression due to lead exposure has been shown to regulate the tumor suppressor, Cyclin-dependent kinase inhibitor 1B (p27Kip1), and down regulation of p26Kip1 has been linked to increased cell proliferation and higher incidences of various cancers." (PMID 25076963, 2014). "Furthermore, haploinsufficiency of CDKN1B is strongly implicated in numerous cancer types, the vast majority of lymphatic origin." (PMID 25213837, 2014). "Moreover, our aCGH analyses of the same series showed that some cases without mutation in the studied genes do have deletions of other cancer genes (for example CDKN1B, ETV6 and UTX are deleted in HD-0205)." (PMID 20678218, 2010). "Thus, a number of single-nucleotide polymorphisms (SNPs) of the CDKN1B gene located within the 12p13.1-p12 chromosome encoding the p27Kip1 protein have been investigated and found to be related to either regulation of p27Kip1 protein expression or susceptibility to various cancers." (PMID 39519258, 2024). "However, the mechanisms by which CDKN1B missense mutations might induce cancer development or haploinsufficiency remain largely obscure." (PMID 33316141, 2021). "However, also in these tumors the frequency of CDKN1B mutation is below the 10% of the cases, partially supporting the old evidence that p27 expression is mainly deregulated at post-transcriptional level in human cancer." (PMID 30065701, 2018). "Interestingly, deletion or mutations of the CDKN1B gene are rare in cancers." (PMID 28477016, 2017). "Moreover, the viral perturbation of host cellular networks reflected disease etiology in that host genes (e.g. CTCF, RHOA, and CDKN1B) identified were frequently essential and significantly associated with Mendelian and orphan diseases, or somatic mutations in cancer." (PMID 27632082, 2016). "The cyclin-dependent kinase inhibitor 1B (CDKN1B or P27KIP1) was initially identified as a cyclin-dependent kinase inhibitor (CDKi) and is frequently found to be mis-regulated in cancer cells." (PMID 39875724, 2025). "The results have shown that the basal expression of CDKN1B was different in cancer cells, but for all other genes, we were unable to provide conclusive evidence." (PMID 40805149, 2025). "Early studies highlighted miR-221’s oncogenic role in cancer, where it was found to promote cell proliferation by targeting cyclin-dependent kinase inhibitors (cyclin dependent kinase inhibitor 1b (CDKN1B/p27), CDKN1C/p57)." (PMID 41369385, 2025). "Mutations in CDKN1B and TCF7L2 have been implicated in the initiation and progression of various cancers." (PMID 40658092, 2025). "The criteria for selecting these CDKN1B genetic changes were (i) their definite or possible clinical significance in human cancers and (ii) their potential effect on p27 subcellular localization and/or p27 phosphorylation." (PMID 39936980, 2025). "The overexpression of miR-221/222 promotes cancer cell proliferation, most likely through their regulation of the CDKN1B expression." (PMID 38476236, 2024). "Previous research suggests that the expression of NOP2 primarily relies on the m5C methylation level, as it can promote cancer cell proliferation through m5C-dependent inhibition of Cyclin-Dependent Kinase Inhibitor 1B (CDKN1B, p27Kip1)." (PMID 38436027, 2024). "In the study, we first investigated the cancer-related roles of CDKN1B’s in 40 tumors with malignancy." (PMID 37432583, 2023). "With the help of bioinformatics, a pan-cancer analysis was conducted on the expression levels of CDKN1B in cancer tissues and adjacent tissues from the TCGA, CPTAC and GEO databases." (PMID 37432583, 2023).
cancer (continued). "The TIMER2 assay was performed to calculate the levels of CDKN1B gene in 40 cancer types from the TCGA database in order to investigate the oncogenic consequences of human CDKN1B." (PMID 37432583, 2023). "Cancers carrying BRAF mutations have increased the expression of cell cycle inhibitors, including CDKN2A, CDKN1A, and CDKN1B." (PMID 38020918, 2023). "Phosphorylation on other sites is potentiated by mitogens or growth factors and in certain cancer cell lines, meaning that phosphorylated CDKN1B found in the cytoplasm is inactive." (PMID 37337185, 2023). "IHC was performed to examine the expression of CDKN1B in STAD, LIHC, and the surrounding normal tissues in order to confirm the variances in CDKN1B expression between cancer tissues as well as surrounding tissues in the databases." (PMID 37432583, 2023). "In the current study, we first addressed a pan-cancer analysis for the CDKN1B gene utilizing the TCGA and GEO databases in various malignancies." (PMID 37432583, 2023). "Low CDKN1B expression was associated with low interferon-γ (p = 0.018), high TIDE signature score (p = 0.065), and decreased cancer-associated fibroblasts (p = 0.002)." (PMID 38248731, 2023). "Numerous studies have demonstrated that CDKN1B’s effects on the cell cycle have a significant role in the formation of cancers." (PMID 37432583, 2023). "CDKN1B is highly expressed in most of cancers, which was also confirmed in STAD and LIHC by IHC in our study." (PMID 37432583, 2023). "However, the loss of CDKN1B may occur in carcinomas containing these tissues." (PMID 38248731, 2023). "While miR-200b-induced CDKN1B degradation promotes cancer cell proliferation, reduced expression of miR-200b was accompanied by an increased expression of RND3, an important regulator of cell migration." (PMID 36140249, 2022). "The expression of CDKN1B was significantly higher in cancer tissues than in the para-cancerous normal tissues." (PMID 35397647, 2022). "CDKN1B is a complex cancer gene because its protein, p27kip1, can act both as an activator or as a repressor of the RB1 tumor suppressor protein, by inhibiting CDK2 or by activating CDK4/Cyclin D, respectively." (PMID 34680217, 2021). "Overall, CDKN1B is mainly dysregulated at the post-transcriptional level in human cancer, which supports our finding of a significantly differentially expressed ceRNA axis." (PMID 34805186, 2021). "In human cancer cells, hsa-miR-24-3p inhibits protein synthesis of CDKN1B, which in turn inhibits CDKN1/2 protein, an essential factor in cell cycle progression." (PMID 35132877, 2021). "Previous work reported that hsa-miR-24-3p induces cell division by inhibiting cell translation of cyclin-dependent kinase inhibitor (CDKN1B) RNA in mammalian cancer cells." (PMID 35132877, 2021). "miR-196b modulates cancer cell proliferation by inhibiting CDKN1B, promoting cancer cell migration and invasion." (PMID 35011637, 2021). "The awareness that CDKN1B haploinsufficiency is involved in cancer development and evolution has become progressively more stringent, thus making CDKN1B a major example of haploinsufficient TSG." (PMID 33316141, 2021). "Although some tumours delete the CDKN1B gene, the major mechanism for downregulation of p27 in cancer is SCF-SKP2-mediated hyperdegradation." (PMID 33166394, 2020). "In line with our expected, miR-455 was found to be significantly up-regulated, but SMAD4 and CDKN1B were significantly down-regulated in cancer." (PMID 31763681, 2020).
cancer (continued). "This is in clear contrast to Rb1G/G; Cdkn1b-/- whose cancer free survival data is shown for comparison purposes." (PMID 30703085, 2019). "The miR-221-3p targets genes at early stage such as Annexin A1 (ANXA1), Cyclin Dependent Kinase Inhibitor 1B (CDKN1B), and multiple genes during advance-stage cancer such as CDKN1B, PTEN, Ring Finger Protein 20 (RNF20), Estrogen Receptor 1 (ESR1) and AKT3." (PMID 31756185, 2019). "Overall, these data indicate that, in primary LBC, CDKN1B mutations are mostly located in the C-terminal portion of p27, possibly contributing to alteration of protein localization and stability that, in turn, may profoundly affect cancer cell proliferation and motility." (PMID 30065701, 2018). "The downregulated genes were associated with cell cycle, TGF-β signaling, FoxO signaling, HIF-1 signaling, and cancer (CDKN1B, FLT3, PDK1, FOXO1, BCL2, ERG), suggesting potential positive regulation of these pathways by SHARP1 to maintain MLL-AF6 AML activity." (PMID 29692408, 2018). "Previously, we and others have demonstrated P27, the cyclin-dependent kinase inhibitor 1B, arrested the cell cycle of cancer cells and contributed to drug-resistance." (PMID 29707241, 2018). "CDKN1B was selected as a probe because it is located in the center of the deletion, which spans > 10 Mb and includes > 50 genes in 80% of cancers with 12p deletion." (PMID 26293672, 2015). "Up-regulation of CDKIs in response to hypoxia restricts cell proliferation in a variety of cancer cell lines, including U2OS cells, and Arnt has been implicated in induced expression of CDKN1B under hypoxic conditions." (PMID 24618291, 2014). "Akt also phosphorylates other proteins commonly implicated in cancer, including GSK3β, BAD, MDM2, and p27 (CDKN1B)." (PMID 24199173, 2013). "In humans, aberrant expression of CDKN1A and/or CDKN1B in various carcinomas of lung, colorectum, cervix, head and neck leads to carcinogenesis by blocking DNA synthesis and inhibiting cell growth." (PMID 23236518, 2012). "Double knockout (dKO) studies in our laboratory revealed that p27 and cyclin D2 are important modifiers of the Inha KO phenotype as Inha/Cdkn1b dKOs had accelerated cancer development, whereas Inha/Ccnd2 dKOs had attenuated tumor formation." (PMID 20676395, 2010). "Dysregulated expression of CDKN1B is a frequent event in several human cancers and it also may contribute to cellular damage and SLE progression." (PMID 39624492, 2024). "The CDKN1B gene encodes the p27Kip1 protein, which can block the production cyclin-dependent kinase (CDK), which is obviously related to the function and survival of cancer cells and alters the prognosis of cancer patients." (PMID 37432583, 2023). "This study firstly provided a pan-cancer analysis of CDKN1B’s involvement in various malignancies." (PMID 37432583, 2023). "The significance of CDKN1B in carcinogenesis is critical for cancer diagnosis and treatment." (PMID 37432583, 2023). "Therefore, the pan-cancer study of CDKN1B can both widen research perspectives and support previous results." (PMID 37432583, 2023). "In many experiments, CDKN1B level is associated with cancer risk, Nevertheless, no pan-cancer analysis has been conducted on CDKN1B in human cancers." (PMID 37432583, 2023). "Additionally, the elevated expression of the CDKN1B gene and protein was validated in several cancer tissues from the patients." (PMID 37432583, 2023). "Based on this finding, we might hypothesize that ZNF143’s potential to change the main cancer signaling pathways may originate from CDKN1B, PIAS4, CTBP2, and ABCC1." (PMID 36675976, 2022).